CD320 (CD320 molecule)
Diseases named in the same sentence as CD320 in open-access papers (continued):
Sharing a sentence is not in itself a finding about the gene and the disease.
cancer (16 papers, 2007 to 2025). A tumor composed of atypical neoplastic, often pleomorphic cells that invade other tissues. "The overexpression of CD320 by cancer cells is likely caused by a high demand for VB12, which is necessary for DNA synthesis and more." (PMID 40565117, 2025). "These have the potential not only to aid in capturing novel conformational states of CD320 for structure determination, but also add to list of potential tools available for diagnostic or therapeutic applications in cancer treatments." (PMID 27411955, 2016). "The cell cycle-associated overexpression of transcobalamin receptor (CD320) in many cancer cells provides a suitable target for delivering chemotherapeutic drugs and cytotoxic molecules." (PMID 22069735, 2011). "Besides, the analysis of stage 1–3 in LIHC based on individual cancer stages was also missing and we need to perform analysis of this section to explore the association between CD320 and the clinical progression of LIHC in the future study." (PMID 38955924, 2024). "Indeed, a prospective assessment of the association between the overexpression of TCN1/TCN2/CD320 or high loads of TCI/TCII/TCII-R on immunohistological analyses of cancer tissues and their resistance to treatment, or for the prognosis, will help to adapt the treatment and survey strategy." (PMID 35631199, 2022). "CD320 involved in VB12 uptake is highly expressed in cancer cells while presenting a low expression profile in normal and differentiated cells." (PMID 40565117, 2025). "Despite promising outcomes presented by potential anti-cancer treatment strategies based on CD320 targeting, they need to be tested on different types of cancer first." (PMID 40565117, 2025). "Another issue of using the VB12 conjugates to target CD320 overexpressing cancer cells is that of the accumulation of drugs and chemotherapeutic agents in the kidneys and liver due to VB12 uptake by these organs." (PMID 40565117, 2025). "CD320 was shown to be overexpressed in many cancers and its potential role as an early cancer biomarker was confirmed in several studies." (PMID 40565117, 2025). "Given the growing interest in CD320 as a novel target for anti-cancer therapy, further in vivo studies are required for the investigation of CD320 targeting effects on systemic cytotoxicity." (PMID 40565117, 2025). "To conclude, CD320 targeting seems to be a promising strategy in cancer treatment, which prevents the death of healthy cells." (PMID 40565117, 2025). "For the application of CD320 targeting therapy, it is essential to first identify the responsiveness of different types of cancer and tissues to this treatment." (PMID 40565117, 2025). "Another report demonstrated that anti-cancer drugs and toxins can be delivered through CD320 to enhance targeted therapeutic effects." (PMID 38955924, 2024). "Two proteins involved in the cellular uptake of cobalamin: transcobalamin II (TCII) and transcobalamin II receptor (TCblR/CD320) have been explored as potential tumor biomarkers as their expression is elevated in cancer cells." (PMID 33478021, 2021). "The present study extends this preliminary observation by demonstrating enhanced targeting and destruction of cancer cells by Saporin conjugated directly to monoclonal antibodies to the extracellular domain of TCblR/CD320." (PMID 24511425, 2013). "Moreover, depending on the expression of CD320, different cancer cells show an inhibition of proliferation to different extents." (PMID 40565117, 2025). "CD320 may serve as a good marker in the detection of different types of cancer and serve as a potential target of new anti-cancer treatments." (PMID 40565117, 2025). "Thus, via targeting CD320, it would be possible to not only selectively kill cancer cells, but also target tumor microenvironments." (PMID 40565117, 2025). "In this scenario, APO-TCN2 could block the binding and delivery of vitamin B12 (HOLO-TCN2) on CD320+ cells, such as malignant tumor cells, thereby limiting their proliferation." (PMID 39493449, 2024).
cancer (continued). "Therefore, CD320-specific antibodies or porphyrins conjugated with cytotoxic drugs could be a safer choice of anti-cancer therapies." (PMID 40565117, 2025). "Thus, it is essential to test the effect of CD320-targeted therapy on different cancers first." (PMID 40565117, 2025). "The high expression of TCII-R in solid cancer cells was demonstrated using TCII-R immune-histological assessments and CD320 RT-qPCR analyses, and using radiolabeled cobalamin or analogs to label tumors, suggesting that the level of cobalamin uptake is associated to cancer aggressiveness." (PMID 35631199, 2022). "Consequently, CD320 may represent a promising anti-cancer therapy target." (PMID 40565117, 2025). "An additional concern in targeting CD320 with VB12–cytotoxic drug conjugates is the existence of other pathways and receptors involved in the uptake of VB12 in cancer and normal cells." (PMID 40565117, 2025). "The simultaneous knockdown of CD320 and LRP2 is necessary to inhibit cancer cell growth, indicating the presence of other pathways involved in VB12 uptake." (PMID 40565117, 2025). "In the context of cancer staging, we observed that in patients with LIHC classified as stage 1, 2, 3, and 4, the CD320 expression levels in tumor tissues were elevated compared to those in the corresponding non-tumor tissues." (PMID 38955924, 2024). "In addition, CD320 expression levels were also found to be correlated with the proliferative phase of the cell cycle, with the highest expression levels occuring between 24 and 48 h after cells begin to proliferate, furthermore, CD320 overexpression was also observed in highly proliferative cancers." (PMID 38955924, 2024). "Other cancer types should now be investigated for this parameter, as well as for TCN2 and CD320 expression levels." (PMID 35631199, 2022). "Although there are some reports about CD320-mediated targeted drugs for treating some cancers, there are no drugs that block or downregulate the CD320 protein to treat patients suffering from LIHC." (PMID 38955924, 2024).
tumor (13 papers, 2007 to 2026). "CD320 was found to be positively associated with tumor microenvironment-forming cells (B cells, CD4+ T cells, macrophages, and dendritic cells)." (PMID 40565117, 2025). "The findings of our research corroborate the notion that CD320 is intricately linked to tumor angiogenesis, as our angiogenesis experiments demonstrated a significant reduction in the angiogenesis capacity of endothelial cells following the knockdown of CD320." (PMID 38955924, 2024). "Both studies indicated that an increased expression of CD320, both in tumors and in tumor microenvironments, is essential for tumor progression." (PMID 40565117, 2025). "Analysis of the databases indicated that CD320 expression levels were greater in LIHC tissues than in non-tumor tissues, and the results of WB, IHC, and single-cell sequencing experiments confirmed this finding." (PMID 38955924, 2024). "In summary, we found that CD320 was predominantly upregulated in tumor vascular endothelial cells and that this alteration affected the capacity of endothelial cells to form blood vessels." (PMID 38955924, 2024). "We observed that CD320 was colocalized with CD31, as demonstrated by IF analysis, and our findings also indicated that the upregulation of CD320 was primarily observed in tumor endothelial cells." (PMID 38955924, 2024). "Single-cell RNA sequencing analysis of LIHC patient tissues revealed increased expression levels of CD320 in tumor endothelial cells compared with those in corresponding non-tumor tissues, and CD320 was colocalized with CD31." (PMID 38955924, 2024). "The cytotoxic effect of mAb-Saporin appears to be dictated primarily by the level of receptor expression and therefore normal primary cells expressing low levels of CD320 were spared while tumor cell lines with higher CD320 expression were destroyed." (PMID 24511425, 2013). "Although CD320 is known to be associated with B-cell survival and proliferation, and FAM3C is a known inducer of osteoblast differentiation, their effect on the tumor microenvironment and their role in MM progression is subject to further research." (PMID 41056512, 2025). "We also found that CD320 may contribute to tumor progression and metastasis by regulating immune cell infiltration within the tumor-immune microenvironment and is a potential novel immunotherapy target for LIHC." (PMID 38955924, 2024). "Furthermore, we observed that the mRNA expression level of CD320 in LIHC tissues was greater than in non-tumor tissues." (PMID 38955924, 2024). "Importantly, while only OS-6 contained a substantial number of CD320+ Plasmocytes and B cells, this primary tumor also measured the greatest percentage (%) of TCN2+ Myeloid cells (relative to all Myeloid cells) at 38.68%." (PMID 39493449, 2024). "We found that CD320 expression was significantly upregulated in tumor vascular endothelial cells." (PMID 38955924, 2024). "Blockage of the CD320 signaling pathway could sensitize tumors to immunotherapy, thereby enhancing the efficacy of tumor immunotherapy." (PMID 38955924, 2024). "Although the expression of CD320 has been shown to be upregulated in many tumors, its functions in tumor vascular endothelial cells in LIHC remain unclear." (PMID 38955924, 2024). "However, the role of CD320 and its regulatory mechanisms in tumor endothelial cells within LIHC are still unclear." (PMID 38955924, 2024). "In summary, we discovered that CD320 was upregulated in tumor vascular endothelial cells in LIHC." (PMID 38955924, 2024). "In this study, we found that CD320 may play an important role in tumor growth and metastasis by impacting endothelium development and angiogenesis." (PMID 38955924, 2024). "In conjunction with our findings, the potential inhibitory effects of CD320 on Rbl1, through an unidentified mechanism may also repress tumor vascular growth." (PMID 38955924, 2024).
tumor (continued). "While only preliminary, both TCN2+ Myeloid and CD320+ Plasmocytes and B cells were identified by scRNA-seq analyses of OSA tumor specimens." (PMID 39493449, 2024). "A significant increase in CD320 expression, compared with that in the respective normal liver tissues, was also detected in 50 pairs of LIHC tumor samples." (PMID 38955924, 2024). "We further examined the protein expression levels of CD320 in LIHC tissues and adjacent non-tumor tissues." (PMID 38955924, 2024). "Importantly, those B lymphocytes of the TIGER database with the greatest increased expression of CD320 included MZB1+ and immunoglobulin producing B cell clusters, commonly found in the marginal zone of germinal centers and tumor TLSs." (PMID 39493449, 2024). "Moreover, similar to CD320, the promoter methylation levels of SORT1 and PSMD14 were considerably lower in tumor tissues than in normal tissues, and there was also a negative correlation between gene expression and promoter methylation levels." (PMID 36959615, 2023). "The results indicated that CD320, PSMD14, and SORT1 protein levels were higher in tumor tissues than in normal tissues, while the level of NTF3 in the normal tissues was higher than that in the tumor tissues." (PMID 36959615, 2023). "CD320 expression was not significantly different between HCC tumor tissues and matched adjacent normal tissues." (PMID 36959615, 2023).
neurologic disorder (1 paper, 2017). "The TCblR/CD320 KO mouse therefore, provides a suitable animal model to study the neurologic disorder associated with Cbl deficiency." (PMID 28545069, 2017). "To understand the etiology of the neurologic disorder associated with Cbl deficiency, we investigated a mutant mouse in which the transcobalamin receptor (TCblR) gene (CD320) was ablated." (PMID 28545069, 2017).
CD320 also shares sentences with these, for which no sentence is quoted: cardiovascular disease (2 papers); melanoma (2); neurodegenerative disease (2); breast carcinoma (1); cobalamin deficiency (1); Diabetes (1); glioblastoma (1); homocystinuria (1); megaloblastic anemia (1); Merkel cell carcinoma (1); Methylmalonic aciduria (1); multiple sclerosis (1); non-small cell lung carcinoma (1); Obesity (1); optic neuropathies (1); Parkinson disease (1); progressive supranuclear palsy (1); renal disease (1); Salmonella Infections (1); Stroke (1); Tremor (1).